TRIM7 (tripartite motif containing 7)
Diseases named in the same sentence as TRIM7 in open-access papers (continued):
Sharing a sentence is not in itself a finding about the gene and the disease.
Sepsis (1 paper, 2022). Sepsis is defined as life-threatening organ dysfunction caused by a dysregulated host response to infection. "This study was to explore the expression of Tripartite Motif 7 (TRIM7) in peripheral blood mononuclear cells (PBMCs) of patients with sepsis and its diagnostic value." (PMID 36402943, 2022). "The green fluorescence intensity representing the expression level of TRIM7 in PBMCs of patients in the sepsis group was the lowest among three groups." (PMID 36402943, 2022). "ROC curve analysis revealed that the area under curve (AUC) of TRIM7 mRNA expression in PBMCs for the diagnosis of sepsis was 0.798, with a 95% confidence interval of 0.691- 0.905, a sensitivity of 73.5%, and a specificity of 77.1%." (PMID 36402943, 2022). "In conclusion, the expression level of TRIM7 in PBMCs of patients with sepsis is significantly down-regulated, which has a certain value for early diagnosis of sepsis and can be used as a supplement to common infection markers in clinical work." (PMID 36402943, 2022). "The receiver operating characteristic (ROC) curve was utilized for evaluating the value of TRIM7 expression for the early diagnosis of sepsis." (PMID 36402943, 2022). "By comparing with other clinical indicators, we can see that TRIM7 mRNA level in PBMCs has certain advantages in the early diagnosis of sepsis." (PMID 36402943, 2022). "The expression of TRIM7 mRNA in PBMCs of the sepsis group was significantly reduced to the lowest level comparing to that of non-septic infection group and control group (p < 0.05)." (PMID 36402943, 2022). "The expression of TRIM7 in PBMCs of patients with sepsis is significantly down-regulated, which has certain clinical value for early diagnosis of sepsis." (PMID 36402943, 2022). "The fluorescence intensity representing the expression level of TRIM7 in PBMCs of patients in the sepsis group was the lowest among three groups." (PMID 36402943, 2022). "ROC curve analysis revealed that the AUC of TRIM7 mRNA expression in PBMCs for the diagnosis of sepsis was 0.798, with a 95% confidence interval of 0.691-0.905, a sensitivity of 73.5%, and a specificity of 77.1%." (PMID 36402943, 2022). "The AUC of TRIM7 mRNA’s level in PBMCs for the diagnosis of sepsis was 0.798, the sensitivity was 73.5%, and the specificity was 77.1%." (PMID 36402943, 2022). "The TRIM7 mRNA expression in PBMCs of the sepsis group was greatly decreased in comparison with that of the non-sepsis infection group and control group (P < 0.05)." (PMID 36402943, 2022). "This study detected the expression of TRIM7 in peripheral blood mononuclear cells (PBMCs) of patients with sepsis at an early stage and analyzed its value in the early diagnosis of sepsis." (PMID 36402943, 2022). "We assume that the down-regulation of TRIM7 expression in PBMCs of sepsis patients may be related to the host’s self-defense after infection." (PMID 36402943, 2022). "Since the change of TRIM7 expression in cell experiments mainly occurs in the early stage of infection, early and dynamic monitoring is required to accurately evaluate the severity of infectious diseases and predict the development of sepsis." (PMID 36402943, 2022). "Our research found that the expression level of TRIM7 in PBMCs of patients with non-septic-infection was lower than that of normal controls, while the expression level of TRIM7 in PBMCs of patients with sepsis was lower than that of patients with non-septic-infection." (PMID 36402943, 2022). "In addition, our prior research also verified that TRIM7 can regulate the expression of inflammatory factors after infection through TLR4 pathway, which makes it an important molecular in the development of sepsis." (PMID 36402943, 2022).
tumor (18 papers, 2017 to 2025). "The truncated form of TRIM7 has been linked to the reduction of tumor growth by promoting apoptosis." (PMID 39205259, 2024). "The ubiquitin ligase TRIM7 has tumor-promoting and tumor-suppressing activities and functions in a variety of biological processes, including innate immunity, ferroptosis regulation, and cell proliferation and migration." (PMID 39943134, 2025). "Our investigation demonstrated for the first time that TRIM7 exerted anti-tumor effects through inducing ferroptosis via inhibiting SLC7A11-GPX4 axis." (PMID 38509147, 2024). "This downregulation is significant as TRIM7 acts as a tumor suppressor, inhibiting the proliferation of GC cells and inducing ferroptosis." (PMID 39205259, 2024). "In vivo experiments and correlation analysis based on clinical specimens further confirmed that TRIM7 inhibited tumor growth through suppressing SLC7A11/GPX4 axis." (PMID 38509147, 2024). "The tumor volume and tumor weight were significantly reduced in the Flag-TRIM7 group compared with those of the other three groups." (PMID 38509147, 2024). "Although chemotherapy resulted in a statistically significant reduction of all tumours, the tumours of the high-TRIM7 group remained larger compared to the low-TRIM7 expressing group." (PMID 39592467, 2024). "In vitro, TRIM7 substantially inhibits the proliferation and migration of tumor cells and promotes cell apoptosis, but its effects are less effective in vivo." (PMID 38791918, 2024). "TRIM7 induced K48-linked polyubiquitination of SLC7A11 protein, further leading to the inhibition of its downstream GPX4 and acting as a tumor suppressor in GC." (PMID 38509147, 2024). "They divided the PDX models into two groups, with low or high TRIM7 expression, and compared the efficacy of adriamycin and methotrexate chemotherapeutics in reducing the tumour burden." (PMID 39592467, 2024). "In contrast, the tumor volume in the animals with TRIM7 overexpression was significantly smaller compared with the control group." (PMID 38509147, 2024). "TRIM7 has been shown to regulate various cellular processes, including autophagy, cell death, migration, and invasiveness of tumor cells." (PMID 39205259, 2024). "For instance, TRIM7 was identified as a tumor suppressor in ccRCC by decreasing the levels of Src protein via the ubiquitin-proteasome pathway, hence exerting a negative regulatory effect on HIF-1 signaling." (PMID 38773612, 2024). "At the same time, we further studied the role of TRIM7 in vivo through subcutaneous tumor formation in nude mice." (PMID 38509147, 2024). "For example, the AP events of several tumor-related genes, such as TRIM7, MLK4, ADNP, and TRAP1, had higher inclusion levels in G1." (PMID 35989380, 2022). "As an E3 ubiquitin ligase, TRIM7 participates in some important biological processes, such as glycogen metabolism and tumor cell proliferation." (PMID 36402943, 2022). "Several data lines suggest that TRIM7 may act as either a tumor suppressor or an oncogene, depending on the context." (PMID 39851497, 2025). "Animals with knockdown of TRIM7 showed significant increase in tumor volume." (PMID 38509147, 2024). "Additionally, TRIM7 targets NF-κB subunit p65 for proteasomal degradation in lung cancer cells and inhibits their proliferation and metastasis, providing more evidence in support of its tumor suppressor role." (PMID 39851497, 2025). "In conclusion, our investigation demonstrated for the first time that TRIM7, as a tumor suppressor, induced ferroptosis via targeting SLC7A11 in GC, which provided a new strategy for the molecular therapy of GC by upregulating TRIM7." (PMID 38509147, 2024). "A total of five tumor antigens with prognostic values were identified, including IGF2BP3, DPCR1, HOXD10, TRIM7, and ZIC5." (PMID 35593226, 2022).
tumor (continued). "Taken together, these results suggested the prognosis‐related tumor antigens including IGF2BP3, DPCR1, HOXD10, TRIM7, and ZIC5 were promising targets of being developed as mRNA vaccines against COAD." (PMID 35593226, 2022). "A total of five selected tumor antigens, including IGF2BP3, DPCR1, HOXD10, TRIM7, and ZIC5 were identified as promising candidates for mRNA vaccine." (PMID 35593226, 2022). "Based on these studies, we speculated that TRIM7 may activate ferroptosis by regulating the SLC7A11/GPX4 axis, thereby inhibiting tumor progression." (PMID 38509147, 2024). "Analysis of tumor immune infiltration showed the elevated expression levels of IGF2BP3, DPCR1, HOXD10, TRIM7, and ZIC5 tended to be correlated with the increased tumor infiltrating B cells, CD8+ T cells, CD4+ T cells, and APCs including macrophages and DCs in COAD patients." (PMID 35593226, 2022).
infection (12 papers, 2021 to 2025). The state of being infected such as from the introduction of a foreign agent such as serum, vaccine, antigenic substance or organism. "There was some loss of infection in cells expressing ΔRING, which may indicate that the binding of TRIM7 to viral proteins alone partially disrupts their function." (PMID 35893676, 2022). "It should be pointed out that TRIM7 was down-regulated in both the lungs and lymph nodes after infection with C. muridarum and P. aeruginosa." (PMID 37686095, 2023). "The TRIM7 gene was the only gene whose expression was decreased in mouse lungs and lymph nodes after both infections and in A549 after P. aeruginosa infection." (PMID 37686095, 2023). "Most interestingly, TRIM7 expression decreased in the lungs and in the lymph nodes after both infections." (PMID 37686095, 2023). "Knockdown of TRIM7 can reduce the inflammatory response, suggesting that TRIM7 can positively regulate the inflammatory response after infection." (PMID 36402943, 2022). "We also show that it is this promiscuous helix-ΦQ motif that allows TRIM7 to restrict infection by both norovirus and Coxsackievirus." (PMID 35893676, 2022). "While Trim7 may play an important role in a yet-to-be-tested MNV infection system, caution is urged in defining Trim7 as a broad-acting antiviral recognizing the products of 3C-like protease cleavage events." (PMID 40464581, 2025). "Deficiency of Trim7 in the infected mice does not alter the sites of infection or the burden of MNV in these mice." (PMID 40464581, 2025). "TRIM7 can also protect the host during infection by reducing cellular apoptosis." (PMID 39205259, 2024). "Researchers speculate that the specific type of virus, infective doses, and duration of infection may contribute to the observed differences in TRIM7’s effects." (PMID 37719674, 2023). "The good specificity may be attributed to that the detection object of TRIM7 expression is PBMCs, which directly participates in the immune reaction after pathogen infection." (PMID 36402943, 2022). "The expression of TRIM7 in PBMCs of individuals with infection is closely related to its biological role in affecting inflammatory response through regulating the TLR4 pathway, and its change trend is consistent with the results of our previous cell experiments." (PMID 36402943, 2022). "To evaluate the impact of Trim7 on the gastrointestinal tissue infection and persistence of MNV, we infected WT and BL6/Trim7+1/+1 littermate-matched mice with MNVCR6 and monitored viral load over 21 days of infection." (PMID 40464581, 2025). "To test if Trim7 has a role in earlier stages of acute MNV infection before MNV titers peak, we challenged WT BL6 and BL6/Trim7+1/+1 littermates with MNVCW3 and harvested tissues 2 days post-infection." (PMID 40464581, 2025). "We investigated the innate immune response to MNVCW3 infection in MLN, spleen, and liver of BL6/Trim7+1/+1 mice at 7 days post-infection by measuring the induction of cytokines via qPCR." (PMID 40464581, 2025). "We inoculated WT BL6 and BL6/Trim7+1/+1 littermates with MNVCW3 and harvested tissues 7 days post-infection." (PMID 40464581, 2025). "Utilizing two independently derived Trim7-deficient mouse lines, we found no changes in the viral burden or tissue distribution of MNV in both an acute and persistent model of infection." (PMID 40464581, 2025). "Others report that Trim7 ubiquitinates stimulator of interferon genes (STING) and mitochondrial antiviral signaling protein (MAVS), leading to a reduced innate immune response and decreased protection against infection." (PMID 40464581, 2025). "Trim7 has been reported to influence host innate immune defenses due to its role in the degradation of STING and MAVS, leading to decreased inflammatory response to infection." (PMID 40464581, 2025). "Similar to the data at 7 days post-infection, we found no detectable differences in MNV genomes in Trim7-deficient or sufficient animals." (PMID 40464581, 2025).
infection (continued). "We orally inoculated STINGGt/Gt Trim7+1/+1 or littermate STINGGt/Gt Trim7WT/+1 controls with MNVCW3 and assessed replication in the MLN, spleen, liver, colon, or ileum via qPCR 7 days after infection." (PMID 40464581, 2025). "The fluorescence intensity of TRIM7 in non-septic infection group was also down-regulated than that of the control group." (PMID 36402943, 2022). "The expression of TRIM7 mRNA in PBMCs of the non-septic infection group was substantially down-regulated than that of control group (p < 0.05)." (PMID 36402943, 2022). "While ZIKV E-WT replicates at lower levels in TRIM7 JEG-3 CRISPR Knockout (TRIM7 KO) cells, no additional difference is observed when infecting with the ZIKV E-K38R mutant (a recombinant virus lacking ubiquitination at E-K38 during infection) compared to WT and TRIM7 KO cells." (PMID 37719674, 2023).
cancer (9 papers, 2020 to 2024). A tumor composed of atypical neoplastic, often pleomorphic cells that invade other tissues. "Recently, the TRIM7 protein has gained attention in cancer studies, because of its association with Ras, Src, and NF-κB signaling pathways." (PMID 32882786, 2020). "Specifically, TRIM7 can inhibit the growth of malignant tumors such as liver cancer, lung cancer, and kidney cancer." (PMID 38509147, 2024). "Consistently, the expression of TRIM7 mRNA and protein in the 38 GC patients admitted to our hospital was significantly lower in the cancer tissues compared with that of the adjacent tissues." (PMID 38509147, 2024). "Our previous study showed that TRIM7, the shortest form of TRIM7 gene, affects cancer progression through regulating NF-κB signaling pathway." (PMID 36042481, 2022). "In hepatocellular carcinoma models, cancer progression was suppressed by TRIM7, which was negatively regulating overactive Src." (PMID 32882786, 2020). "At the molecular level, TRIM7 promoted apoptosis via the NF-κB signaling pathway and suppressed the proliferation and migration of cancer cells." (PMID 32882786, 2020). "And in hepatocellular carcinoma, TRIM7 (GNIP1) promoted malignant proliferation of cancer cells." (PMID 36042481, 2022). "TRIM7, also known as glycogenin-interacting protein 1 (GNIP1), was found to exert protective or detrimental effect in various cancers by different molecular mechanisms." (PMID 36474231, 2022). "RNF90 (also called TRIM7/GNIP), was identified as a RING-type E3 ubiquitin-protein ligase in various cancer pathological conditions." (PMID 34512666, 2021).
bacterial infections (1 paper, 2024). "There is only one report describing the role of TRIM7 in bacterial infections; during L. monocytogenes infection, TRIM7 reduces bacteria burden in mice by promoting K63 ubiquitination of ATG7 and induces autophagy." (PMID 39205259, 2024).
infectious disease (1 paper, 2022). A disorder directly resulting from the presence and activity of a microbial, viral, or parasitic agent in humans. "The outcomes of the present research revealed that the reduced level of TRIM7 expression in PBMCs may indicate a more serious condition in infectious diseases." (PMID 36402943, 2022).
TRIM7 also shares sentences with these, for which no sentence is quoted: breast carcinoma (1 paper); colorectal cancer (1); diabetes mellitus (1); metastatic melanoma (1); pancreatic cancer (1); viral diseases (1).